IRX1 (iroquois homeobox 1)
Synonyms: IRXA1; IRX-5
Tractability: No criterion of Open Targets' tractability assessment is met for any kind of drug.
Gene: Protein-coding gene on chromosome 5 (3,595,832 to 3,601,403, forward strand). Ensembl gene ENSG00000170549.
Subcellular location: Nucleus
Subcellular location (Human Protein Atlas): Golgi apparatus; Nucleoplasm
Pathways (Reactome):
Developmental Biology: Nephron development
Gene Ontology:
Molecular function: DNA-binding transcription repressor activity, RNA polymerase II-specific; sequence-specific DNA binding; sequence-specific double-stranded DNA binding; DNA-binding transcription factor activity, RNA polymerase II-specific; RNA polymerase II cis-regulatory region sequence-specific DNA binding; DNA binding
Biological process: negative regulation of transcription by RNA polymerase II; cell development; neuron differentiation; regulation of transcription by RNA polymerase II; metanephros development; positive regulation of gene expression; proximal/distal pattern formation involved in metanephric nephron development; regulation of DNA-templated transcription; specification of loop of Henle identity
Cellular component: chromatin; nucleus
Genetic constraint (gnomAD): Loss-of-function variants: 22 observed, 27.93 expected, observed/expected ratio (o/e) 0.79, 90% interval 0.56 to 1.12. The synonymous counts are far from expectation, so gnomAD's model fits this gene poorly and the ratio says little. Missense variants: 750 observed, 623.65 expected, observed/expected ratio (o/e) 1.2, 90% interval 1.13 to 1.28. Synonymous variants: 358 observed, 293.08 expected, observed/expected ratio (o/e) 1.22, 90% interval 1.12 to 1.33.
Homologues: Orthologues: chimpanzee IRX1 (100% identical), macaque IRX1 (99% identical), pig IRX1 (94% identical), mouse Irx1 (91% identical), rat Irx1 (90% identical), dog IRX1 (89% identical), rabbit IRX1 (79% identical), tropical clawed frog irx1 (68% identical), guinea pig IRX1 (66% identical), zebrafish irx1a (60% identical). Paralogues in human: IRX3 (44% identical), IRX4 (32% identical), IRX5 (30% identical), IRX6 (29% identical), IRX2 (28% identical), MKX (17% identical).
Diseases named in the same sentence as IRX1 in open-access papers:
IRX1 is named in the same sentence as 52 diseases in open-access papers, as found by Europe PMC text mining. Sharing a sentence is not in itself a finding about the gene and the disease. The quoted sentences say what the papers report.
gastric cancer (15 papers, 2014 to 2025). A primary or metastatic malignant neoplasm involving the stomach. "BDKRB2, a downregulated gene associated with angiogenesis in IRX1-transfected gastric cancer cells, is a downstream target gene of IRX1 and was identified as a potential target for anticancer strategies." (PMID 36980893, 2023). "For gastric cancer, an SNP (rs11134044) has been associated with differential expression of IRX1 and correlated with cancer risk by a genome-wide association study (GWAS)." (PMID 33256112, 2020). "IRX1 encodes a member of the iroquois homeobox protein 1 family, which plays a role in pattern formation in both vertebrate embryos and invertebrate species and has been implicated in suppression of gastric cancer." (PMID 40868849, 2025). "Furthermore, the hypermethylation of IRX1 was found to be associated with lymph node metastasis status in early gastric cancer, highlighting its potential as a biomarker." (PMID 36980893, 2023). "While little is known about IRX1 in general, a transfection study in gastric cancer cell lines identified several putative target genes of IRX1 with a role in vasoconstriction and vasolidation." (PMID 37828025, 2023). "In this regard, a vasculogenic mimicry (VM) model established using the SGC-7901 gastric cancer cell line showed that in human umbilical vein endothelial cells, tubular formation was significantly inhibited in IRX1-transfected cells." (PMID 36980893, 2023). "The expression of PRMT5 and IRX1 revealed opposite correlations at the RNA and protein levels in both gastric cancer cell lines and tissues." (PMID 36980893, 2023). "Recently, IRX1 was identified as a potential tumor suppressor gene in head and neck squamous cell carcinoma and gastric cancer." (PMID 36316707, 2022). "BDKRB2, an angiogenesis-related gene, demonstrated as a direct IRX1 target gene and was reported to be involved in gastric cancer progression." (PMID 34938313, 2021). "The promoter region of IRX1 is located in a CpG island and hypermethylation of IRX1 has been found in gastric cancer, head and neck squamous carcinoma, and other cancer entities." (PMID 33256112, 2020). "In gastric cancer, IRX1 acts a tumor suppressor through downregulation of BDKRB2, FGF7, and HIST2H2BE expression and inhibiting angiogenesis and cell proliferation." (PMID 33256112, 2020). "An Iroquois homeobox (IRX) family protein, IRX1 is reported as tumor suppressor gene in gastric cancer." (PMID 28423671, 2017). "Consequently, restoring IRX1 expression in two gastric cancer cell lines inhibited growth, invasion, and tumorigenesis in vitro and in vivo." (PMID 33256112, 2020). "Iroquois homeobox 1 (IRX1) is an homeobox-containing transcription factor playing a role in embryonic development and suspected to act as a tumor suppressor gene in head and neck squamous cell carcinoma, gastric cancers and glioma." (PMID 32759814, 2020). "IRX1 is located on cytoband 5p15.33 and the loss of this chromosomal region (LOH; loss of heterozygosity) has been reported in different tumor types including gastric cancer, cervix carcinoma, colorectal cancer, and lung cancer." (PMID 33256112, 2020). "Hypermethylation of IRX1 has been found in gastric cancer or head and neck squamous carcinoma." (PMID 33256112, 2020). "Integration analysis of SNPs and gene expression profile revealed that FOXL1 regulated the most important DEGs of IRX1, SOX1, and MSX1 with risk associated SNP loci, which may serve as candidate biomarkers for diagnosis and prognosis of gastric cancer." (PMID 27403158, 2016). "Similarly, the inhibition of a microRNA upregulated in GC cells, miR-150, which targets IRX1 sequences, restrains proliferation, migration, and invasion while facilitating apoptosis of gastric cancer cells by upregulating IRX1 and represses tumor growth in vivo." (PMID 36980893, 2023).
gastric cancer (continued). "In a more recent study, PRMT5 has been shown to be overexpressed in a large cohort of human gastric tumors and to contribute to increased recruitment of DNA methyltransferase 3A (DNMT3A) to the promoter region of the tumor suppressor gene, Iroquois homeobox 1 (IRX1), in gastric cancer cells." (PMID 30613353, 2018).
head and neck squamous cell carcinoma (6 papers, 2012 to 2023). A squamous cell carcinoma that arises from any of the following anatomic sites: lip and oral cavity, nasal cavity, paranasal sinuses, pharynx, larynx, and salivary glands. "In head and neck squamous cell carcinoma (HNSCC), the promoter region of IRX1 was found to be mutated in 45% of analyzed patients, and its decreased expression was identified." (PMID 36980893, 2023). "In contrary, the overexpression of SLC5A8 together with IRX1 and EBF3 may be involved in the transforming growth factor beta signaling pathway, which is often disrupted in head and neck squamous cell carcinoma." (PMID 31754358, 2019).
leukemia (6 papers, 2016 to 2022). A malignant (clonal) hematologic disorder, involving hematopoietic stem cells and characterized by the presence of primitive or atypical myeloid or lymphoid cells in the bone marrow and the blood. "Intriguingly, IRX1-positive leukemia blasts emerged only from HSCs or MPPs, whereas HOXA9-positive blasts emerged from all four HSPC compartments." (PMID 36042201, 2022). "Screening of RNA-seq data from 100 leukemia/lymphoma cell lines showed overexpression of IRX1, IRX3, and IRX5 in megakaryoblastic and myelomonocytic AML cell lines, chosen as suitable models for studying the regulation and function of these homeo-oncogenes." (PMID 35328612, 2022). "Downregulation of IRX1 expression was frequently observed in several cancer cell lines compared to leukemia and was also found in NSCLC cell lines." (PMID 33256112, 2020).
osteosarcoma (6 papers, 2016 to 2023). A usually aggressive malignant bone-forming mesenchymal neoplasm, predominantly affecting adolescents and young adults. "Increased expression of IRX1 was also observed in osteosarcoma cell lines and tissues and was strongly related to promoter hypomethylation." (PMID 36980893, 2023). "Overexpression of IRX1 in osteosarcoma cells (ZOS and MNNG-HOS) increased the degradation of IκBα and the nuclear translocation of NF-κB p65." (PMID 36980893, 2023). "Hypomethylation of the promoter of IRX1, leading to overexpression of IRX1, was reported in clinical osteosarcoma primary samples and osteosarcoma cell lines." (PMID 36072791, 2022). "In osteosarcoma, activation of Iroquois homeobox 1 (IRX1), as a prometastatic protein, directly increases CXCL14 expression, and promotes osteosarcoma metastatic activity via elevated CXCL14/NF-κB signaling." (PMID 26733763, 2016). "Moreover, hypomethylation of iroquois homeobox 1 (IRX1) has been involved in osteosarcoma metastasis via induction of CXCL14/NF‐kB signaling." (PMID 37369946, 2023). "Moreover, metastasis activity was found to be altered in osteosarcoma cell lines upon modulation of IRX1 expression." (PMID 36072791, 2022). "In another example, IRX1 promoter hypomethylation detected in serum DNA of patients with osteosarcoma might be a potential biomarker for predicting lung metastasis in osteosarcoma." (PMID 34660788, 2021). "Additionally, the effect of IRX1-knock down (shIRX) was investigated in 143B osteosarcoma cells." (PMID 33256112, 2020). "Furthermore, negative modulation of IRX1 in osteosarcoma cell lines profoundly decreased metastatic activity, including migration, invasion and resistance to anoikis, in vitro, and in murine models, it was related to lung metastasis." (PMID 36980893, 2023).
North Carolina macular dystrophy (4 papers, 2017 to 2025). North Carolina macular dystrophy (NCMD) is a non-progressive autosomal dominant macular disorder of congenital or infantile onset characterized by loss of central vision, the accumulation of drusen in the macula and atrophy of photoreceptor cells with a variable phenotype at macular examination. "North Carolina Macular Dystrophy (NCMD), a rare autosomal dominant disorder, arises from noncoding single nucleotide variants (SNVs) near PRDM13 or duplications overlapping DNase I hypersensitive sites (near PRDM13/IRX1)." (PMID 41210874, 2025).
acute myeloid leukemia (3 papers, 2022 to 2023). Acute myeloid leukemia (AML) is a group of neoplasms arising from precursor cells committed to the myeloid cell-line differentiation. "Accordingly, screening for aberrant IRX gene activities in acute myeloid leukemia (AML) revealed overexpression of IRX1, IRX3 and IRX5 in subsets of patients, identifying these genes as oncogenes for this type of malignancy." (PMID 36833225, 2023). "Analysis of public profiling data from acute myeloid leukemia (AML) patients revealed aberrant activity of IRX1 in addition to IRX3 and IRX5, indicating an oncogenic role for these TALE homeobox genes when deregulated." (PMID 35328612, 2022). "Moreover, aberrant expression of IRX homeobox genes IRX1, IRX2, IRX3 and IRX5 has been detected in hematopoietic malignancies, including B-cell precursor acute lymphoblastic leukemia (BCP-ALL), T-cell ALL, and some subtypes of acute myeloid leukemia (AML)." (PMID 36833225, 2023). "Using the myeloid TALE-code, we have recently detected physiological activity of TALE homeobox gene IRX1 exclusively in megakaryocyte erythroid progenitors (MEPs) during early myelopoiesis, and aberrant expression of IRX1, IRX3 and IRX5 in particular subtypes of acute myeloid leukemia (AML)." (PMID 36233173, 2022).
lung carcinoma (3 papers, 2020 to 2022). "The chromosomal region 5p15.33, that harbors the IRX1 gene, has been reported as a susceptibility locus for lung cancer." (PMID 33256112, 2020). "Since it has been reported that the IRX1 gene is localized in a lung cancer susceptibility locus, the epigenetic regulation and function of IRX1 was investigated in lung carcinogenesis." (PMID 33256112, 2020). "Here, we report that IRX1 expression is negatively correlated with the hallmark EMT a lung cancer data set." (PMID 33256112, 2020). "Here, we observed an inverse correlation of IRX1 and DNMT3A or EZH2 expression in primary lung cancers suggesting a causal relation between aberrant expression of epigenetic modifiers and IRX1 silencing." (PMID 33256112, 2020). "It has been reported that the chromosomal region 5p15.33 harbors a lung cancer susceptibility locus and we analyzed the epigenetic regulation of IRX1 that is located in this specific cytoband." (PMID 33256112, 2020). "In our work, we identified Iroquois homeobox 1 (IRX1) from the lung cancer susceptibility locus 5p15.33, as an epigenetically silenced target gene." (PMID 33256112, 2020). "IRX1 is localized on cytoband 5p15.33 and it has been reported that this region harbors a susceptibility locus for lung cancer." (PMID 33256112, 2020). "Loss of IRX1 expression by its promoter hypermethylation can serve as a diagnostic and prognostic lung cancer biomarker." (PMID 33256112, 2020). "Thus, loss of IRX1 expression by its promoter hypermethylation can serve as a diagnostic and prognostic lung cancer biomarker." (PMID 33256112, 2020). "However, low methylation level (<10%) were observed in IPAH tissues and this indicates that DNA hypermethylation of IRX1 is rather associated with lung cancer than with IPAH." (PMID 33256112, 2020). "To analyze the reactivation of IRX1 expression in lung cancer cell lines, we treated A427 and A549 cells with an inhibitor of DNMT (Aza/5-Aza-2′-deoxytidine) and an inhibitor of HDAC (TSA/trichostatin A)." (PMID 33256112, 2020). "Inhibition of DNA methyltransferase (DNMT) activity reactivated IRX1 expression in human lung cancer cell lines." (PMID 33256112, 2020). "Our data suggest that IRX1 acts as an epigenetically regulated tumor suppressor in the pathogenesis of lung cancer." (PMID 33256112, 2020). "We also analyzed the regulation of IRX1 as a potential target for lung cancer diagnosis and its reactivation as a novel therapeutic option for epigenetic editing." (PMID 33256112, 2020). "In A427 and A459 lung cancer cell lines, we observed a dosage dependent induction of IRX1 expression by the DNMT inhibitor (20-fold induction by 5 or 10 μM Aza, respectively)." (PMID 33256112, 2020). "In our study, we investigated the epigenetic regulation and the tumor suppressor function of IRX1 in the pathogenesis of lung cancer." (PMID 33256112, 2020). "In our study, we wanted to understand the regulation of IRX1 in lung cancer and its molecular contribution to tumorigenesis." (PMID 33256112, 2020). "Here, we revealed by GSEA that IRX1 expression is negatively correlated with E2F- and Myc-targets in several lung cancer data sets." (PMID 33256112, 2020). "However, in lung cancer, IRX1 inhibits expression of the pro-apoptotic gene BAX, supporting a role of IRX factors in the (de)regulation of cell survival." (PMID 35328612, 2022). "Re-expression of IRX1 significantly inhibited lung cancer cells growth compared to control cells." (PMID 33859751, 2021). "Additionally, inhibition of DNMT activity by 5-Aza-2′-deoxycytidine reactivated the expression of IRX1 in two lung cancer cell lines." (PMID 33256112, 2020). "We also performed in vitro experiments to explore the functional role of other methylation drivers (IRX1, TBX5 and HSPB6) in lung cancer cell lines." (PMID 33859751, 2021). "To investigate the cellular function of IRX1, we fused its ORF with an enhanced yellow fluorescent protein (EYFP) and transfected this construct in A549 lung cancer cells." (PMID 33256112, 2020).
lung carcinoma (continued). "In addition, we validated the tumor-suppressive role of IRX1, TBX5 and HSPB6 in lung cancer." (PMID 33859751, 2021). "Moreover, all of the eight novel hypermethylation driver genes (PCDH17, IRX1, ITGA5, HSPB6, TBX5, ADCY8, GALNT13 and TCTEX1D1) were successfully validated in an independent cohort via a pyrosequencing approach, with an AUC of 0.965 for prediction of lung cancer patients." (PMID 33859751, 2021). "The remaining eight genes are newly identified methylation drivers in lung cancer, including 5 known cancer methylation driver genes in other cancer types (HSPB6, IRX1, ITGA5, PCDH17, TBX5) and 3 novel genes that had not been previously reported (ADCY8, GALNT13 and TCTEX1D1)." (PMID 33859751, 2021).
cardiac hypertrophy (2 papers, 2018 to 2024). "The role if any played by DNER, REG3A, and IRX1 to diastolic dysfunction and cardiac hypertrophy is not reported, although genetic variants of the IRX1 gene were recently reported to contribute to the pathogenesis of congenital heart disease." (PMID 29556499, 2018).
type 2 diabetes (2 papers, 2025). "Our analysis revealed that genetic variants in the human orthologs of dmd-5 (DMRTA2 and DMRTB1) and irx-1 (Iroquois homeobox (IRX) protein family genes (IRX1–6)) were associated with metabolic traits, including body weight, cardiovascular disease, and type 2 diabetes." (PMID 40766245, 2025). "In addition, we discovered seven other potential key transcriptional regulators of gene expression networks in type 2 diabetes: Etv1, Irx1 and Foxp1 (alpha cells); Ehf, Hhex and Tcf4 (delta cells); and Zfhx3 (macrophages)." (PMID 39508880, 2025).
age (1 paper, 2025). A temporal measurement of the time period elapsed since an identifiable point in the life cycle of an organism. "In the FinnGen database, we found that four of the identified lifespan-related transcription factors—dmd-5, irx-1, nhr-25, and unc-62—are also associated with human metabolic diseases, emphasizing their potential as targets for interventions addressing age-related pathologies." (PMID 40766245, 2025).
autoimmune disorders (1 paper, 2025). "The rs32727 variant, mapped to a long non-coding RNA region near the IRX1 gene, which has been associated with rheumatoid arthritis, suggests a new shared locus for autoimmune disorders." (PMID 40473712, 2025).
Cachexia (1 paper, 2022). Severe weight loss, wasting of muscle, loss of appetite, and general debility related to a chronic disease. "The results showed that the mRNA and protein expression levels of IRX1 in SAT were higher than that in VAT in cancer cachexia mice, which was consistent with the results above." (PMID 36316707, 2022). "IRX1 expression in SAT was found to be negatively correlated with SAT area and was involved in the lipid metabolism of the pathological process in cachexia." (PMID 36316707, 2022). "Then we compared the mRNA and protein levels of IRX1 in SAT and VAT of cancer cachexia mice." (PMID 36316707, 2022).
chronic gastritis (1 paper, 2023). Inflammation of the stomach that is chronic in nature. "A relationship between H. pylori and IRX1 was observed by Guo and colleagues, who identified that the levels of IRX1 promoter methylation in tissue DNA from Hp+ chronic gastritis were higher than observed in Hp- chronic gastritis tissues, 55.30% ± 13.17 versus 5.20% ± 6.31, respectively (p < 0.01)." (PMID 36980893, 2023).
Down syndrome (1 paper, 2024). "Finally, a recent study by Sato and colleagues detected IRX1 mutations in Down syndrome associated myeloid leukemia, and showed that IRX1 boosts megakaryocyte/erythroid differentiation, highlighting its role in early myelopoiesis." (PMID 39689089, 2024).
keloid (1 paper, 2022). An irregularly shaped, elevated mark on the skin caused by deposits of excessive amounts of collagen during wound healing. "In terms of expression level, BMP4, MSX1, TBX2, SIX1, DLX5, and DLX2 were lowly expressed, while HAND2, IRX1, EDN1, and MEF2C were highly expressed in keloid fibroblasts." (PMID 35047146, 2022).